NLRP7 (NLR family pyrin domain containing 7)
Diseases named in the same sentence as NLRP7 in open-access papers (continued):
Sharing a sentence is not in itself a finding about the gene and the disease.
cancer (13 papers, 2013 to 2024). A tumor composed of atypical neoplastic, often pleomorphic cells that invade other tissues. "In relation to cancer, increased NLRP7 expression has been reported to be associated with poor prognosis of colorectal cancer, endometrial cancer, and to play a crucial role in testicular tumorigenesis." (PMID 34203890, 2021). "Considering that IBD patients have an increased risk of CRC and the function of NLRP7 in cancers remains unclear, we decided to explore the contribution of NLRP7 to colorectal tumorigenesis." (PMID 33838681, 2021). "Several genes, including ARRDC5, ELF5, FIBCD1, LINC00494, NLRP7, and L1CAM, have been implicated in various aspects of cancer progression and metastasis." (PMID 39697539, 2024). "This comprehensive analysis emphasized ARRDC5 and NLRP7 as the most consistently dysregulated genes across multiple cancer types, underscoring their critical role in cancer biology." (PMID 39697539, 2024). "The clinical relevance of NLRP7 in this rare cancer highlights its potential therapeutic promise as a molecular target to treat resistant GC patients." (PMID 36980199, 2023). "Nevertheless, the relationship between the expression of NLRP7 and the prognosis of patients suffering from malignant tumors were still unclear." (PMID 36276158, 2022). "There are seldom studies involved in the correlation between NLRP7 inflammasome and malignant tumors." (PMID 36276158, 2022). "While increasing literature exists about the involvement of NLR members in cancer development, few studies are available for NLRP7." (PMID 35203462, 2022). "Through the present study, we propose that NLRP7 is a key actor of CC growth that should be categorized among the important pathophysiological factors for the development of this cancer." (PMID 34203890, 2021). "In a recent study from our group, we hypothesized that NLRP7 might contribute to cancer cell camouflage." (PMID 36980199, 2023). "The authors proposed that the expression of NLRP7 in the invasive front of cancer may provide malignant tissue with a suitable environment for their growth and spread through inducements to immunosuppression." (PMID 35203462, 2022). "Therefore, we decided to focus on cytokines and chemokines that are regulated by NLRP7 in cancer cells." (PMID 33838681, 2021). "Furthermore, NLRP7 expression is increased in certain type of cancers such as testicular and endometrial cancers." (PMID 24137163, 2013). "In this study, we examined the expression patterns of seven core genes (ARRDC5, ELF5, FIBCD1, LINC00494, NLRP7, L1CAM) across multiple cancer types using a combination of unpaired and paired samples, along with data from the TCGA-GTEx datasets." (PMID 39697539, 2024). "Through comprehensive genomic, epigenomic, and transcriptomic dissections, we pinpointed ARRDC5, ELF5, FIBCD1, LINC00494, NLRP7, and L1CAM as possible prognostic indicators across multiple cancer types." (PMID 39697539, 2024). "GSDMC, NLRP7, CASP5, PYCARD, IL18, IL1B and GSDMA were significantly upregulated in 22, 18, 18, 18, 18, 16 and 17 types of cancers, respectively." (PMID 35246158, 2022). "In our study, drug-sensitivity analysis revealed that the expression of NLRP7, NLRP2, NOD1, and CASP6 was positively correlated with some or most drugs in the cancer therapeutic response portal database." (PMID 34226539, 2021). "NLRP1, NLRP3, NLRC4, NLRP6, NLRP7, and NLRP12 have mixed roles in the pathogenesis of a variety of cancers as reviewed here in details." (PMID 33584697, 2020). "Hence, our study strongly suggests that NLRP7, similar to NLRP3 and NLRP12, functions in an inflammasome-independent manner to facilitate cancer progression." (PMID 36980199, 2023). "Altogether, these findings strongly suggest that NLRP7, similar to NLRP3 and NLRP12, may function in an inflammasome-independent manner in cancer." (PMID 34203890, 2021).
cancer (continued). "We observed that NLRP7 (n = 8), AIM2 (n = 10), CASP8 (n = 6), GSDMA (n = 5), GSDMB (n = 8), and GSDMC (n = 12) mainly showed hypomethylation in most cancers, and PLCG1 (n = 11), NLRP6 (n = 13), ELANE (n = 11), CASP6 (n = 5), NLRC4 (n = 12), and PYCARD (n = 8) showed hypermethylation in most cancers." (PMID 35246158, 2022). "However, no study has yet investigated NLRP7 involvement in the etiology of this cancer." (PMID 34203890, 2021).
infection (5 papers, 2016 to 2025). The state of being infected such as from the introduction of a foreign agent such as serum, vaccine, antigenic substance or organism. "Silencing of the gene encoding NLRP7 in human macrophages leads to a reduction in IL-1β and IL-18 release during infection with the bacterium S. aureus or L. monocytogenes, suggesting that NLRP7 activation mediates an inflammasome response." (PMID 41062723, 2025). "Additional insights into the mechanisms of activation identified that the NBD of NLRP7 binds to ATP and acts as an ATPase during infection with S. aureus." (PMID 39351983, 2025). "NLRP7 inflammasome formation has also been observed in THP-1 macrophages during infection with the bacterium Mycobacterium bovis, and in amnion epithelial cells stimulated with fibroblast-stimulating lipopeptide from the bacterium Mycoplasma salivarium." (PMID 41062723, 2025). "Treatment with M. bovis significantly upregulated the expression of NLRP7 mRNA at 14 h post-infection (hpi)." (PMID 27043315, 2016). "These apparently contradictory findings are probably best reconciled by assuming that NLRP7 serves as a negative regulator of inflammation in quiescent cells, while in response to a proper stimulus, such as infection, NLRP7 promotes inflammasome assembly and caspase-1 activation." (PMID 32550001, 2020). "To investigate whether the NLRP7 inflammasome plays a role in the production of TNF-α and CCL3 besides IL-1β and IL-18, we silenced NLRP7 or ASC in THP-1 macrophages prior to infection, which significantly attenuated M. bovis-induced upregulation of TNF-α, CCL3 and IL-1β at the mRNA level." (PMID 27043315, 2016).
reproductive diseases (1 paper, 2023). "NLRP7 is related to innate immune signaling, and has positive and negative effects on inflammasome responses, and NLRP7 mutations contribute to reproductive diseases." (PMID 37228386, 2023).
NLRP7 also shares sentences with these, for which no sentence is quoted: endometrial cancer (3 papers); embryonal carcinoma (2); glioma (2); preeclampsia (2); bacterial infection (1); Beckwith-Wiedemann syndrome (1); benign tumor (1); Burkitt lymphoma (1); childhood cancer (1); complete moles (1); COVID-19 (1); developmental delay (1); Endometrium (1); inflammation (1); leukemia (1); mesothelioma (1); placental cancer (1); prostate carcinoma (1); rectal cancer (1); Stillbirth (1); Stroke (1); testicular seminoma (1); trophoblastic gestational neoplasia (1).